MCM10 (minichromosome maintenance 10 replication initiation factor)
Diseases named in the same sentence as MCM10 in open-access papers (continued):
Sharing a sentence is not in itself a finding about the gene and the disease.
cancer (continued). "In pan-cancer, the putative CNA of MCM10 was demonstrated in." (PMID 37848534, 2023). "Notably, in some cancer types, such as OV, READ and THYM, patients with high MCM10 expression instead have a better prognosis, showing an opposite trend to other cancer types." (PMID 37848534, 2023). "Unlike other MCMs, MCM10, which is not part of the core helicase complex, is a critical determinant of origin activation and its levels are limiting in cancer cells." (PMID 39086679, 2023). "One interesting observation showed that decreasing the levels of MCM10 led to decreased growth in cancer cells, whereas normal cells were not affected." (PMID 39086679, 2023). "We incorporated information from the TCGA and GTEx databases to supplement the expression of MCM10 in pan-cancer samples because the TCGA database lacked normal samples." (PMID 37848534, 2023). "Although many studies have shown increased MCM10 expression in highly proliferating tumors, direct evidence linking MCM10 and cancer phenotype is yet lacking." (PMID 35813483, 2022). "Furthermore, we combined the results of the perturbation-induced reversal effects on the expression levels of MCM2 and MCM10 and the sensitivity correlation between perturbations and MCM2 and MCM10 from the Cancer Therapeutics Response Portal database." (PMID 35056094, 2021). "Overexpression of MCM10 in MCF 7 cells, monitored by stable expression of FLAG tag, did not affect the proliferation rate or any of the key hallmarks of cancers." (PMID 30135378, 2018). "Most importantly, MCM10 depletion reduced the growth of cancer cells but not normal cells." (PMID 37848534, 2023). "Moreover, we also showed that the MCM10 inhibitors Suramin and its analogues (NF157, NF546, and PPADS) can be used as potential anti‐cancer agents for ESCC, but are warranted to deconstruct the precise mechanisms and effective targets of these drugs before its clinical use." (PMID 34185429, 2021). "However, the potential utility of reducing MCM10 in cancer therapy is not clear; nonetheless, it can decrease initiation of DNA replication." (PMID 30135378, 2018). "MCM10 initiates DNA replication by activating MCM replication complex, which implies that its dysregulation may contribute to uncontrollable proliferation, thereby, leading to cancer development." (PMID 30135378, 2018). "In most types of cancer (except for adipose, bone, and tooth cancers), the expression of MCM2 and MCM10 was higher in cancerous tissues than non-cancerous tissues." (PMID 35056094, 2021). "The top-ranked genes by NGP-PLK1, MCM2, MCM3, MCM7, MCM10 and SKP2 might coordinate to promote cell cycle related processes in cancer but not normal cells." (PMID 22838965, 2012). "Our results suggest that the top-ranked genes by NGP-PLK1, MCM2, MCM3, MCM7, MCM10 and SKP2 might coordinate to promote cell cycle related processes in cancer but not normal cells." (PMID 22838965, 2012).
hematopoietic diseases (1 paper, 2023). "However, this has also been observed in neonatal human patients, where mutations in MCM10 have been associated with specific hematopoietic diseases." (PMID 37437546, 2023). "Considering this, it could be hypothesized that these specific hematopoietic diseases in MCM10-deficient human patients were caused by an alteration of RUNX1 expression." (PMID 37437546, 2023).
neurological disorders (1 paper, 2022). "Most importantly, several DEGs such as CX3CL1, SEMA3F, OPHN1, POLA2, MCM10 and POLD3 were found to be associated with neuronal/brain process and genome stability, that is known to be relevant during neurological disorders." (PMID 36267332, 2022).
MCM10 also shares sentences with these, for which no sentence is quoted: esophageal cancer (3 papers); gastric cancer (3); cholestasis (2); esophageal squamous cell carcinoma (2); immune dysfunction (2); triple-negative breast carcinoma (2); abdominal aortic aneurysm (1); anemia (1); coronary atherosclerosis (1); COVID-19 (1); diabetes (1); endometrial endometrioid adenocarcinoma (1); endometrial mixed adenocarcinoma (1); endometrial serous adenocarcinoma (1); epilepsy (1); Ewing sarcoma (1); glioblastoma (1); Hypercholesterolemia (1); hypothyroidism (1); immunodeficiency disease (1); infection (1); large-cell lung carcinoma (1); lung squamous cell carcinoma (1); lymph node metastasis (1); Malignant fibrous histiocytoma (1); multiple sclerosis (1); Pancytopenia (1); psoriasis (1); rheumatoid arthritis (1); round cell liposarcoma (1).
A further 5 diseases each share a sentence with MCM10 in 1 paper.